ANGPTL4 (angiopoietin like 4)
Diseases named in the same sentence as ANGPTL4 in open-access papers (continued):
Sharing a sentence is not in itself a finding about the gene and the disease.
tumor (continued). "Overexpression of ANGPTL4 induces transcriptional signatures of tumor invasion and metastasis, proliferation and differentiation, and inhibition of apoptosis." (PMID 36747689, 2023). "In a similar line, we also observed increased expression of LIPG and corresponding lipase activity after silencing of ANGPTL4 in ECs, but in our case, we found reduced angiogenesis and tumor growth." (PMID 38086791, 2023). "The activation of TGFβ signaling pathway in hypoxic microenvironment was shown to promote the release of ANGPTL4 from tumor cells as an important mechanism to promote angiogenesis." (PMID 37091977, 2023). "ANGPTL4 is a multifaceted protein that functions in the tumor microenvironment to promote tumor growth, angiogenesis, and chemoresistance." (PMID 36795484, 2023). "The hypoxic microenvironment of Scissor_C1 induced high ANGPTL4 expression that then enhanced vascular permeability in endothelial cells, resulting in greater likelihood of tumor invasion and metastasis." (PMID 37091977, 2023). "Based on the expression and biological localization analyses of L/R pairs, we identified two L/R pairs (LAMB3/CD44 and ANGPTL4/SDC1) with high reliability between tumor cells and PCs." (PMID 37138324, 2023). "Patients with the highest (top 25%) expression of ANGPTL4 in tumor tissue had reduced overall survival (OS) and disease-free survival, (p = 0.043 and p = 0.059 (log-rank test)." (PMID 37291514, 2023). "When pshRNA‐ANGPTL4 was given to mice, ANGPTL4 expression and the tumour were significantly reduced, and tumour energy metabolism was simultaneously significantly decreased." (PMID 35285130, 2022). "Since ANGPTL4 is regulated by several transcription factors at the crossroad of metabolism and tumor development, the signaling pathway leading to its upregulation after G-1 exposure remains to be determined." (PMID 36430793, 2022). "highlights six genes (VEGFA, KDR, ESM1, CD34, PECAM1, and ANGPTL4), but only four of them were expressed by endothelial cells while VEGFA and ANGPTL4 were mainly expressed by tumor cells." (PMID 36423636, 2022). "And the Pearson correlation coefficients between NNMT and CRYZ, and SERPING1 and ANGPTL4 across all TCGA tumor samples were 0.4, 0.43, and 0.62, respectively." (PMID 36386816, 2022). "ANGPTL4 is a multifaceted secreted protein that regulates lipid metabolism, vessel permeability, inflammation, proliferation, and tumor progression." (PMID 35860030, 2022). "It was found that the expressions of GPX4 and FTH1 in A549 xenograft tumours were significantly reduced by irradiation, which was reversed by the upregulation of ANGPTL4." (PMID 36050447, 2022). "Collectively, our in vivo results further verified that ANGPTL4 was essential for hypoxic exosomes induced radioresistance in tumours at least partly through GPX4-mediated ferroptosis inhibition." (PMID 36050447, 2022). "Recently, it has been shown that ANGPTL4 also plays a critical role in tumor growth and progression." (PMID 36467503, 2022). "Under the same treatment with gefitinib, the growth rate and weight of the tumor in the ANGPTL4-shRNA + G group were lower than those in the control + G group (p < 0.05)." (PMID 36467503, 2022). "Previous studies have shown that ANGPTL4 had higher expression in tumor patients and induced a malignant phenotype of tumor cells, i.e., proliferation, migration, and drug resistance." (PMID 35461343, 2022). "Alex's group demonstrated that short-chain fatty acids stimulate tumor promoter angiopoietin-like 4 synthesis in human COAD cells." (PMID 35967794, 2022). "In particular, we demonstrated how ANGPTL4 regulates the metabolism of BCAAs, thereby regulating tumor progression of OS through the activation of mTOR signaling pathway, but we do not know exactly how various receptors are involved." (PMID 35461343, 2022). "Analysis of the Human Protein Atlas database revealed that ANGPTL2 and ANGPTL5 were highly expressed in HCC tumor tissues, while ANGPTL4 was decreased." (PMID 35692877, 2022).
tumor (continued). "It is well known that ANGPTL4 plays a pivotal carcinogen mediator in tumour growth, proliferation, invasion, angiogenesis and metastasis." (PMID 36050447, 2022). "The staining intensity of ANGPTL4 was higher in tumor cells when compared with normal bile duct epithelia." (PMID 35392474, 2022). "Although the role of ANGPTL4 in the metabolic regulation was compelling, the impacts of ANGPTL4 on tumor progression were confusing." (PMID 35461343, 2022). "When the autocrine regulatory effect of ANGPTL4 becomes explicit, its activity as a paracrine factor in the tumour hypoxic microenvironment is also our main concern." (PMID 36050447, 2022). "As for tumor tissues, upregulation of HIF1α activates the transcription of the pro-angiogenic factors ANGPTL4 and VEGFA." (PMID 36074318, 2022). "In this study, we found that the extracellular ANGPTL4 protein was enriched in hypoxic tumour-derived exosomes and endowed radioresistance of NSCLC cells under hypoxia." (PMID 36050447, 2022). "In situ immunofluorescence assay showed that ANGPTL4 was expressed synregionally with HIF-1α at high levels in mouse xenograft tumours." (PMID 36050447, 2022). "Transplant of EO771 tumor cells into the mammary glands of angiopoietin-like 4-null mice resulted in significantly reduced tumor growth with limited blood vessel density." (PMID 35435599, 2022). "The experimental results showed that compared with the characteristic glycolysis of tumour cells, ANGPTL4 had a more significant effect on oxidative phosphorylation but had a less significant effect on glycolysis." (PMID 35285130, 2022). "High ANGPTL4 expression was significantly correlated with lymph node metastasis and advanced tumor stage (p = 0.013 and p = 0.031, respectively)." (PMID 35392474, 2022). "To confirm this effect in vivo, we constructed a xenograft mouse model and obtained results consistent with those in vitro experiments, i.e., the hypoxic exosomal ANGPTL4 drastically enhanced the radioresistance of NSCLC xenograft tumours to irradiation." (PMID 36050447, 2022). "ANGPTL4 promotes tumor metastasis by signaling through the transforming growth factor β (TGF-β) pathway." (PMID 35392474, 2022). "ANGPTL4 is highly expressed in various cancers, but the regulation of energy metabolism in tumours remains to be determined." (PMID 35285130, 2022). "Consistent with the results of in vitro experiments, ANGPTL4 overexpression facilitated the tumour growth and reduced the anti-tumour effect of radiotherapy." (PMID 36050447, 2022). "Our data showed that high expression of ANGPTL4 in CCA tissues was significantly correlated with advanced tumor stage and metastasis." (PMID 35392474, 2022). "One report revealed an additional tumor-promoting activity of ANGPTL4 by interacting with integrin 1/5, which increases O2- levels, and activates the Src, PI3K/PKB, and ERK pathways." (PMID 35392474, 2022). "But the overexpression of ANGPTL4 significantly increased Ki67 expression level in tumour tissue, indicating again that ANGPTL4 protected cells from irradiation and promoted cell proliferation." (PMID 36050447, 2022). "Previous data also suggested that ANGPTL4 limited tumor aggressiveness and invasiveness by preventing angiogenesis and vascular permeability." (PMID 36430793, 2022). "Downstream molecules of the TGF-β signaling pathway related to tumor metastasis, including ANGPTL4 and IL11, were also significantly upregulated in SE than SN patients." (PMID 34557402, 2021). "The first group included CA9, NDUFA4L2, EGLN3, BHLHE41, VWF, IGFBP3, and ANGPTL4, whose expression levels were coordinately decreased during tumor progression." (PMID 34046336, 2021). "Considering that tumor stromal cells interact with tumor cells during tumor growth, the protein expression level of ANGPTL4 was further tested in the co‐culture system of GBC‐SD cells with GCAFs/NFs." (PMID 34331381, 2021).
tumor (continued). "Under hypoxic conditions, the colonization of tumor cells at distant sites is enhanced through the upregulation of angiopoietin-like 4 (ANGPTL4) that disrupts contacts between endothelial cells and favors the passage of tumors cells through the blood vessels." (PMID 34360919, 2021). "In this study, we found that ANGPTL4 knockdown resulted in activated CAFs in the tumor microenvironment." (PMID 34405010, 2021). "This study revealed that DNA promoter methylation silenced the ANGPTL4 gene to induce the activation of CAFs in the tumor microenvironment and formed a positive feedback loop with the EMT of CRC cells, ultimately promoting the invasion and metastasis of CRC." (PMID 34405010, 2021). "It is believed that ANGPTL4 is also responsible for tumor development, vascular stability, glycemic homeostasis, lipid metabolism, cell differentiation, wound healing, inflammation development, and the regulation of redox potential." (PMID 34445141, 2021). "But levels of ANGPTL4 protein in tumor tissues are significantly lower than that in non-tumor tissues of the same HCC patients." (PMID 34540685, 2021). "Collectively, this evidence indicates that the proangiogenic and antiangiogenic roles of ANGPTL4 are tissue-specific and strongly dependent on the tumor properties." (PMID 33726754, 2021). "Angiopoietin‐like protein 4 (ANGPTL4) has been shown to regulate tumor angiogenesis and metastasis, and predict poor prognosis." (PMID 34331381, 2021). "By manipulating redox homeostasis and activating several pro-survival mechanisms such as FAK/Src, PI3K/Akt, Erk signaling, ANGPTL4 markedly sharpens the resilience of tumor cells and confers anoikis resistance." (PMID 33946986, 2021). "In our study, the different gene expression profiles between GCAFs and NFs were first analyzed using Affymetrix chips, proving that the ANGPTL4 related to tumor angiogenesis was significantly upregulated in GCAFs." (PMID 34331381, 2021). "The angiogenesis cluster—besides containing some of the same previous ECM proteins—comprised the angiopoietin ANGPTL4 and other genes that are known to act in tumour-induced angiogenesis (AQP1, RAMP1, HSPB1, MYLK), for a total of 21 entries." (PMID 34439343, 2021). "In vivo, the overexpression of ANGPTL4 was found to inhibit the metastasis of tumor cells in lung tissues." (PMID 34405010, 2021). "The up-regulated ANGPTL4 contributed to tumor angiogenesis, growth, metastasis, invasion, and reduced OS of patients." (PMID 34291084, 2021). "There was a significant positive correlation between expressions of CRNDE and ANGPTL4 in CRC tumor tissues (r = 0.417, p < 0.001)." (PMID 34680556, 2021). "Immunofluorescence and Western blot were used to identify the signaling pathways by which ANGPTL4 mediated tumor metastasis." (PMID 34405010, 2021). "Together, these findings depicted that silencing ANGPTL4 in tumor cells ultimately promoted cancer metastasis by activating fibroblast signaling in the tumor microenvironment." (PMID 34405010, 2021). "Angiopoietin-like 4 (ANGPTL4) is a matricellular protein, initially described as an angiogenic factor in settings of vascular injury or tumor development." (PMID 32405335, 2020). "Strong ANGPTL4 expression in nude mouse xenografts also inhibited metastasis through suppression of tumor cell migration and invasiveness." (PMID 32928141, 2020). "ANGPTL4 was also reported to prevent metastasis through inhibition of angiogenesis, tumor cell motility and invasion." (PMID 32641980, 2020). "Suppression of ANGPTL4 expression did abolish tube formation, which reinforced the role of upregulated ANGPTL4 in promoting tumor malignancy." (PMID 33196458, 2020). "ANGPTL4 serves an important role in the tumour microenvironment, especially that which is hypoxia-induced." (PMID 31963541, 2020). "In breast cancer cells, lncRNA RAB11B-AS1 recruits RNA polymerase II to upregulate VEGFA and ANGPTL4 expression and promotes tumor angiogenesis." (PMID 32993787, 2020).
tumor (continued). "Recently, the ANGPTL4 protein was reported to promote or prevent tumor growth, metastasis and angiogenesis depending on the different cancer types." (PMID 32928141, 2020). "ANGPTL4 knockdown enhanced cell apoptosis and sensitized tumor cells to drug treatment, confirming that ANGPTL4 played a key role in anoikis resistance." (PMID 33196458, 2020). "Genome-wide expression profiling identified a group of genes within the angiogenesis pathway, including angiopoietin-like 4 (Angptl4), fibroblast growth factor 1 (Fgf1), and pleiotrophin (Ptn) as targets of activated PPARγ favoring tumor angiogenesis." (PMID 32785018, 2020). "On the other hand, several reports also suggest that ANGPTL4 enhances tumor metastasis by triggering endothelial disruption or alteration of MMP expression in tumor cells." (PMID 32641980, 2020). "Using the TCGA database, we analysed MAP3K8, CCL20, VEGFC, and ANGPTL4 gene expression levels in both normal tissue and tumour tissue samples." (PMID 32019546, 2020). "To further understand how ANGPTL4 inhibits tumor migration, we performed next-generation RNA sequencing on three groups of MDA-MB-231 cell lines: the NC (231 NC), vector (231 vector) and ANGPTL-overexpressing groups (231 ANGPTL4 OE)." (PMID 32928141, 2020). "On the other hand, evidence also suggests that full-length or C-terminal ANGPTL4 functions as a tumor promoter that enhances tumor proliferation and metastasis 25-28." (PMID 32641980, 2020). "A positive correlation between plasma ANGPTL-4 and NFκB (p< 0.01) in the tumor was detected in CC group." (PMID 31741709, 2019). "Studies have demonstrated the role of ANGPTL-4 in promoting increased tumor cell progression and aggressiveness." (PMID 31741709, 2019). "Previous studies have demonstrated that ANGPTL-4 expression is regulated by hypoxia in both endothelial cells and tumor cells." (PMID 31741709, 2019). "In tumor tissue in the CC group, ANGPTL-4 showed a significant positive correlation with IL-1β (p < 0.01), a positive correlation with TNF-α (p ≤ 0.05), and a positive correlation with NFκB (p < 0.05)." (PMID 31741709, 2019). "ANGPTL4 expression has been shown to increase with tumor malignancy, and multiple oncogenic signaling was able to positively regulate ANGPTL4 expression." (PMID 31717924, 2019). "Using the regression analysis we verified, in CC group, that ANGPL-4 content in the tumor was associated positively with IL-1β and MCP-1 contents; in the mesenteric adipose tissue with IL-1β content, and ANGPTL-4 plasma level with NFκB content in tumor." (PMID 31741709, 2019). "What’s more, knockdown of ANGPTL4 rescued the tumor suppressive phenotype of LMX1A overexpression, which indicated that LMX1A upregulates ANGPTL4 to exert its role." (PMID 31557193, 2019). "An increase in plasma and tumor ANGPTL-4 was detected in cancer cachexia patient, as well as an association to proinflammatory factors such as NFκB, IL-1β and MCP-1." (PMID 31741709, 2019). "Vascular endothelial growth factor (VEGF) and angiopoietin-like 4 (ANGPTL4) are also HIF-1-regulated angiogenic genes playing a pivotal role in tumor invasiveness and metastasis." (PMID 31487965, 2019). "Prior to establishing the bEnd.3 in vivo tumor model to study the effects of R-propranolol, ANGPTL4 expression in bEnd.3 cells in vitro was investigated." (PMID 31701018, 2019). "ANGPTL4 has been also reported to be an apoptosis survival factor capable of preventing metastasis by inhibiting vascular growth and protecting from tumour cell invasion." (PMID 31745224, 2019). "We first found that ACM-conditioned TNBC cells upregulated the expression of ANGPTL4, a secreted glycoprotein whose effect on tumor progression is known to be tumor microenvironment- and tumor-type dependent." (PMID 31602400, 2019). "Knockdown of ANGPTL4 in TNBC MDA-MB-231 cells with shRNA decreased ACM-induced tumor cell metastatic growth in the brain and attributed to survival in a mouse model." (PMID 31602400, 2019).
tumor (continued). "In general, our results showed that LMX1A exerts its tumor suppressive role by activating ANGPTL4 to inhibit C-Myc." (PMID 31557193, 2019). "In WSC group the plasma level of ANGPTL-4 was positively correlated with IL-10 (p=0.04) and IL-15 (p=0.02) in the tumor and with IL-15 (p < 0.01) in the mesenteric adipose tissue." (PMID 31741709, 2019). "The results showed that while LMX1A overexpression expectedly inhibited tumor growth, the inhibitory effect was reversed by knockdown of ANGPTL4." (PMID 31557193, 2019). "Specifically in CC-group, a positive correlation was found between ANGPTL-4 levels and those of IL-1β, TNF-α, and NFκB in tumor, along with an association between ANGPTL-4 levels with IL-1β and MCP-1 levels in tumor; and ANGPTL-4 and IL-1β levels in MES." (PMID 31741709, 2019). "Taken together, our results indicate that the tumor suppressive role of LMX1A at least partly dependent on the up-regulation of ANGPTL4." (PMID 31557193, 2019). "Among the potential LMX1A target genes, angiopoietin-like 4 (ANGPTL4) has been reported to be an important tumor suppressor and thus was selected for further validation and research." (PMID 31557193, 2019). "Another significantly upregulated mRNA, angiopoietin-like 4 (ANGPTL4), has been reported to prevent metastasis by inhibiting blood vessel growth and tumor cell motility and invasiveness." (PMID 30814490, 2019). "Recently, it has been demonstrated that tumor-derived ANGPTL4 suppressed in vitro vascular tube formation and proliferation of human umbilical vascular endothelial cells, through suppression of ERK signaling." (PMID 29389861, 2018). "In preclinical models treatment with Ab-ANGPTL4 had indeed significantly demonstrated to block angiogenesis, motility and metastasis by destroying tumor-favorable microenvironment." (PMID 29389861, 2018). "For instance, a recent study showed that tumor tissues had lower levels of ANGPTL4 than non-tumor tissues of HCC patients." (PMID 29389861, 2018). "ANGPTL4 was previously demonstrated to prevent tumour metastasis by inhibiting tumour cell motility and invasiveness." (PMID 30241392, 2018). "In vivo suppression of ANGPTL4 led to higher accumulation of cisplatin-DNA adducts in primary and metastasized tumors, and a reduced metastatic tumor load." (PMID 30342537, 2018). "TGF-β regulates the expression of ANGPTL4 via a Smad3-signaling pathway promoting extravasation of tumor cells and their ability to colonizing lung tissue." (PMID 29389861, 2018). "A recent paper support dual role for ANGPTL4 in urothelial carcinoma progression, either as a tumor suppressor or oncogene, in response to microenvironmental context." (PMID 29389861, 2018). "PGE2 binds to EP1 and activates the EP1 signaling pathway, which in turn promotes tumor expression of ANGPTL4 and cANGPTL4 via activation on transcriptional activator (STAT) 1 (STAT1)." (PMID 30049845, 2018). "Some groups reported that ANGPTL4, through its action on both vascular and tumor compartments, prevents the metastatic process by inhibiting vascular activity as well as tumor cell motility and invasiveness." (PMID 29389861, 2018). "In fact, although its expression did not correlates with overall survival, high expression level of ANGPTL4 relates with the depth of tumor invasion and venous invasion." (PMID 29389861, 2018). "Using a tumor array, they demonstrated an increase in ANGPTL4 in almost 80% of UM tumors, with elevating expression of either VEGF or ANGPTL4 in 99% primary UM tumors." (PMID 30049845, 2018). "ANGPTL4 stimulates tumour cell proliferation, supports anchorage-independent growth and confers anoikis resistance, so promoting in vivo tumourigenesis." (PMID 29739381, 2018). "This is enabled by microenvironmental TGFβ that induces or upregulates ANGPTL4 expression in disseminating tumor cells on their way to secondary metastatic sites." (PMID 29100268, 2017).